KRT24 (keratin 24)
Synonyms: CK-24; K24; KA24; FLJ20261; MGC138169; MGC138173
Tractability: No criterion of Open Targets' tractability assessment is met for any kind of drug.
Gene: Protein-coding gene on chromosome 17 (40,697,991 to 40,703,752, reverse strand). Ensembl gene ENSG00000167916.
Subcellular location (Human Protein Atlas): Cytosol; Intermediate filaments
Pathways (Reactome):
Developmental Biology: Differentiation of Keratinocytes in Interfollicular Epidermis in Mammalian Skin; Formation of the cornified envelope; Keratinization
Gene Ontology:
Molecular function: protein binding; structural constituent of skin epidermis; structural molecule activity
Biological process: epithelial cell differentiation; intermediate filament organization; morphogenesis of an epithelium
Cellular component: extracellular exosome; cytoskeleton; cytosol; keratin filament
Genetic constraint (gnomAD): Loss-of-function variants: 31 observed, 38.25 expected, observed/expected ratio (o/e) 0.81, 90% interval 0.61 to 1.09. The upper end of that interval is the gene's LOEUF score, 1.09, which puts it in group 4 of 6, group 1 being the genes least tolerant of losing a copy. Missense variants: 466 observed, 524.82 expected, observed/expected ratio (o/e) 0.89, 90% interval 0.82 to 0.96. Synonymous variants: 183 observed, 208.86 expected, observed/expected ratio (o/e) 0.88, 90% interval 0.78 to 0.99.
Homologues: Orthologues: chimpanzee KRT24 (98% identical), macaque KRT24 (93% identical), dog KRT24 (86% identical), pig KRT24 (86% identical), mouse Krt24 (70% identical), rat Krt24 (68% identical), guinea pig KRT24 (66% identical). Paralogues in human: KRT10 (52% identical), KRT12 (51% identical), KRT14 (50% identical), KRT16 (49% identical), KRT27 (48% identical), KRT13 (47% identical), KRT15 (47% identical), KRT28 (46% identical), KRT25 (46% identical), KRT17 (46% identical), KRT26 (45% identical), KRT9 (44% identical), and 56 more.
Diseases named in the same sentence as KRT24 in open-access papers:
KRT24 is named in the same sentence as 15 diseases in open-access papers, as found by Europe PMC text mining. Sharing a sentence is not in itself a finding about the gene and the disease. The quoted sentences say what the papers report.
pterygium (2 papers, 2021 to 2022). A wedge-shaped fibrovascular lesion arising from the bulbar conjunctiva and extending to the cornea. "In one previous microarray study, KRT24 was identified as upregulated in pterygium; however, we could not confirm this in independent specimens, suggesting a variable expression." (PMID 34769520, 2021).
brain tumors (1 paper, 2019). "While KRT24, itself, has not been studied in the context of glioma, it has been experimentally determined to be associated with MIB1 and MIB2, which are involved in Notch signaling pathway in brain tumors." (PMID 31475119, 2019).
colon cancer (1 paper, 2020). "The TCGA results indicated that SPIB, KRT24, PHLPP2, PLP1, BEST4, CA7, and C11orf86 were all downregulated, while KRT80, SLC39A10, AJUBA, FOXQ1, and CLDN1 exhibited upregulated levels in colon cancer." (PMID 32633726, 2020).
psoriasis (1 paper, 2022). An autoimmune condition characterized by red, well-delineated plaques with silvery scales that are usually on the extensor surfaces and scalp. "KRT15, KRT24, KRT31, KRT37, KRT78 are differentially expressed in psoriasis, while KRT5 and KRT14 are specific for AD." (PMID 35874668, 2022).
tumor (7 papers, 2019 to 2026). "We observed close colocalization of MUC4 and CA125 in a subpopulation of tumor cells and a stronger KRT24 signal corresponding to these cells in two HVs." (PMID 40527915, 2025). "KRT24 has also been proved to be a potential tumor suppressor." (PMID 37183243, 2023). "Considering abundant expression of KRT24 in normal esophagus and loss of expression in ESCC, we speculate a tumor suppressor role for KRT24 in ESCC." (PMID 31438645, 2019). "In the case of other types of KRT (KRT13, KRT14, KRT24) in HNSCC, OSCC, and neoplastic oral mucosa, decreased protein levels were observed in the tumor sample compared to the margin/healthy tissue, which is consistent with our results." (PMID 39000463, 2024).
cancer (3 papers, 2022 to 2024). A tumor composed of atypical neoplastic, often pleomorphic cells that invade other tissues. "There still lacks research about KRT24 in cancer biology till now." (PMID 37183243, 2023).
KRT24 also shares sentences with these, for which no sentence is quoted: infection (2 papers); adenoma (1); bladder cancer (1); bladder tumors (1); colonic polyps (1); colorectal cancer (1); glioma (1); hyperplastic polyp (1); ovarian carcinoma (1).